CHL1 (cell adhesion molecule L1 like)
Diseases named in the same sentence as CHL1 in open-access papers (continued):
Sharing a sentence is not in itself a finding about the gene and the disease.
depression (10 papers, 2016 to 2024). "Two genome-wide transcription studies initially found the neural cell-adhesion molecule L-1-like protein (CHL-1) to be a potential biomarker for depression." (PMID 27555379, 2017). "Transcriptomic research has indicated that the neural cell-adhesion molecule L-1-like protein (CHL-1) could serve as a potential biomarker for depression, as discovered in two early genome-wide transcription studies." (PMID 39469623, 2024). "Indeed, cell adhesion proteins, including those coded by CHL1 and ITGB3, were shown to play key roles in neurogenesis and synaptogenesis, which in turn, are crucial for remission from depression." (PMID 29163031, 2017). "Moreover, single-nucleotide polymorphisms in neuronal cell adhesion genes involved in synaptic plasticity and identified in the two latter studies performed with human LCLs, namely, CHL1 and ITGB3, were recently shown to affect treatment response in depressive disorders." (PMID 27845776, 2016).
lung cancer (8 papers, 2009 to 2022). A malignant neoplasm involving the lung. "In our previous study, we found that CHL1 gene polymorphisms enhanced lung cancer susceptibility in northeast China." (PMID 34718336, 2021). "In this paper, we conducted hospital-based case-control study to explore the relationship between CHL1 gene polymorphism and lung cancer susceptibility." (PMID 29568376, 2018). "We performed this case-control study to estimate the connection between CHL1 gene polymorphism and lung cancer susceptibility." (PMID 29568376, 2018). "Genome Wide Association Study (GWAS) had found that CHL1 gene polymorphism had a link with lung cancer." (PMID 29568376, 2018). "In conclusion, we demonstrated that there was a link between CHL1 gene and lung cancer susceptibility in northeast of China." (PMID 29568376, 2018). "As far as we are aware, this paper firstly investigated the connection between CHL1 gene polymorphism and lung cancer susceptibility." (PMID 29568376, 2018). "Overall, our study may indicate that CHL1 gene may increase lung cancer susceptibility in northeast of China." (PMID 29568376, 2018). "Besides, we investigated the association between CHL1 gene polymorphism, tobacco exposure and lung cancer susceptibility." (PMID 29568376, 2018). "In addition, T allele of rs425366 in CHL1 gene increased lung cancer susceptibility." (PMID 29568376, 2018). "In the future study, it will be especially necessary to investigate the biological function of CHL1 gene in lung cancer." (PMID 29568376, 2018). "Meanwhile, recent research showed that the up-regulation of CHL1 gene and increase of CHL1 mRNA level were found in lung cancer." (PMID 29568376, 2018). "Thirdly, we lacked other gene-environmental interaction to verify the connection between CHL1 gene and lung cancer." (PMID 29568376, 2018). "The frequency (FD) and the level (LDav) of the CHL1 mRNA decrease in lung cancer (ADC and SCC types)." (PMID 21408220, 2011). "Furthermore, CHL1 expression in esophageal and lung cancer is significantly correlated with a favorable outcome." (PMID 32284790, 2020). "Until now, the biological mechanism of CHL1 gene in lung cancer is still an issue." (PMID 29568376, 2018). "The aim of this study is to explore the association between CHL1 rs425366 polymorphism and lung cancer susceptibility in northeast of China." (PMID 29568376, 2018). "Our results showed that there was statistically significant association between CHL1 rs425366 polymorphism and lung cancer susceptibility in northeast of China." (PMID 29568376, 2018). "However, also there were frequent cases of the CHL1 mRNA level increase in metastatic tumors, for example, in stomach and lung cancer." (PMID 21408220, 2011). "However, the increase of the CHL1 mRNA level was statistically significant only in lung cancer −64% (16 of 25, P<0.01)." (PMID 21408220, 2011). "Encouragingly, we also found this TUBB3+CD68 TAM subset in a 10× scRNA-seq dataset of human non–small cell lung cancer (NSCLC) biopsy with strong expression of neuronal genes including BMP7, SHANK, CHL1, and PAX6." (PMID 36206343, 2022). "Hence rigorous research will be needed to clarify the speculation about CHL1 gene and lung cancer." (PMID 29568376, 2018).
autism (7 papers, 2006 to 2022). Persistent deficits in social interaction and communication and interaction as well as a markedly restricted repertoire of activity and interest as well as repetitive patterns of behavior. "The involvement of cell migration in the pathophysiology of autism is also implicated by the altered expression of CHL1, a novel neural cell adhesion molecule that is involved in neurite migration, outgrowth, connectivity, and survival." (PMID 16709250, 2006). "Deficiency in CHL1 has been shown to be associated with mental and motor impairments as well as with alterations in exploratory and emotional behavior in mice, characteristics that are often associated with autism." (PMID 16709250, 2006).
Cognitive impairment (7 papers, 2011 to 2025). Abnormal cognition is characterized by deficits in thinking, reasoning, or remembering. "Many genes have been implicated to play a role: CRBN and CNTN4 have been suggested to cause typical 3p deletion syndrome, and the CHL1 gene has been proposed to play an additional role in cognitive impairment." (PMID 24778888, 2014). "Moreover, loss of CHL1 was proposed to play an additional role on the cognitive impairment of the affected individuals." (PMID 21457564, 2011). "The 3p deletion involved four pathogenic genes (CHL1, CNTN6, CNTN4, ITPR1) associated with cognitive impairment, ataxia, and motor dysfunction." (PMID 41384039, 2025). "In the limited number of case studies with anomalies restricted to the CHL1 gene, the dysmorphic features have been varied but there is usually some degree of cognitive impairment." (PMID 24778888, 2014). "Overall the region spans less than 1 megabase and includes only one Refseq gene named CHL1 which has been previously proposed as responsible for cognitive impairment in individuals with 3p terminal deletions." (PMID 21457564, 2011). "Interestingly, Frints hypothesized that a reduction equal to 50% of chl1 in the developing brain marked cognitive deficit." (PMID 32028920, 2020).
glioblastoma (7 papers, 2006 to 2022). The most malignant astrocytic tumor (WHO grade IV). "In the present study, we investigated the effects of CHL1 on proliferation indexes and activation of Akt1 and Erk signaling by siRNA in U-87 MG human glioblastoma and human U251 and SHG-44 glioma cells." (PMID 29089868, 2017). "To determine whether the tumor formation of glioblastoma oncogenicity is dependent upon CHL1, we reduced CHL1 expression using CHL1-siRNA combined with EntransterTM-in vivo, which was intratumorally injected to specifically knockdown endogenous CHL1 expression in vivo." (PMID 29089868, 2017). "We first used Western blot to evaluate and compare the expression of CHL1 protein in HEB and three human glioma/glioblastoma cell lines." (PMID 29089868, 2017). "A similar pattern of cell viability inhibition in response to CHL1 knockdown was observed in both SHG44 glioma and U-87 MG glioblastoma cells, with remarkable viability inhibition observed at both 72 h and 96 h time points (p < 0.01 vs. controls at both time points)." (PMID 29089868, 2017). "In this context, a cut-off value of CHL1 hypermethylation has been established to stratify unmethylated and methylated cases, as seen with MGMT hypermethylation, which has been useful for predicting both PFS and OS in glioblastoma." (PMID 28178655, 2017).
glioma (7 papers, 2010 to 2024). A benign or malignant brain and spinal cord tumor that arises from glial cells (astrocytes, oligodendrocytes, ependymal cells). "A recent study found potential for CKMT1B expression as a prognostic biomarker in glioma; similarly, alterations in CHL1 expression have been associated with development and metastasis of many types of cancer." (PMID 39132489, 2024). "DDX11, also known as CHL-1, is able to promote cell proliferation, metastasis, and migration in human glioma cells." (PMID 30841487, 2019). "Our combined results confirmed for the first time that in contrast to findings about CHL1 in most other cancer types, CHL1 functions in promoting cell proliferation, metastasis and migration in human glioma cells both in vitro and in vivo." (PMID 29089868, 2017). "The presence of senescence in response to CHL1 knockdown indicates the potential role of CHL1 in promoting cell survival during the development of glioma." (PMID 29089868, 2017). "We reduced CHL1 expression using EntransterTM-R4000-mediated CHL1-siRNA transfection inU251, SHG44 and U-87 MG glioma cells to specifically knock down endogenous CHL1 expression." (PMID 29089868, 2017). "To address this issue, we systematically investigated the roles of CHL1 in glioma behaviors mainly using siRNA targeting CHL1 in glioma cells." (PMID 29089868, 2017). "Although intratumoral injection of siRNA targeting CHL1 in the present study reduces the volume increase of glioma xenografts, the growth inhibition efficacy is limited." (PMID 29089868, 2017). "In addition, CHL1, which is also negatively associated with long-term survival in GBM patients, promotes the survival of glioma cells by inhibiting the apoptosis of glioma cells via the phosphatidylinositol 3-kinase (PI3K)/AKT signaling pathway." (PMID 38019838, 2023). "In the present work, CHL1 was lowly expressed in human astroglia cells, but was highly expressed in human glioma cell lines, suggesting its potential roles in the development of glioma." (PMID 29089868, 2017). "Whether the effect of CHL1 on glioma is closely related to the ERK and AKT signaling pathways has not been reported." (PMID 29089868, 2017). "In summary, our work preliminarily demonstrated the roles of CHL1 in the development of gliomas, which may provide a scientific basis for the molecular targeting treatment of gliomas." (PMID 29089868, 2017). "Targeting the role of CHL1 may represent a promising therapeutic means for the management of glioma." (PMID 29089868, 2017). "Although CHL1 expression and function have been reported in several tumors, the roles of CHL1 in the development of glioma remain unclear." (PMID 29089868, 2017). "Taken together, these results indicated that CHL1-dependent anti-apoptosis in glioma cells may be partially mediated by regulation of the death receptor signaling pathway composed of Bax, Bcl-2 and active caspase-3." (PMID 29089868, 2017). "In summary, CHL1 is vitally involved in the regulation of the occurrence and development of glioma." (PMID 29089868, 2017). "However, CHL1 expression in the development, metastasis, and progression of gliomas both in vitro and in vivo remains unclear." (PMID 29089868, 2017). "We then explored whether glioma cell oncogenicity is dependent upon CHL1." (PMID 29089868, 2017). "After glioma cells were transfected with CHL1 siRNA or negative control siRNA, cells were fixed and stained for β-galactosidase activity using the X-Gal substrate at 37°C for 24 h." (PMID 29089868, 2017). "The discrepancy of our findings with those observed in non-glia-derived tumors may be due to the fact that glioma cells express a variety of molecules that interact with CHL1." (PMID 29089868, 2017).
ovarian carcinoma (6 papers, 2013 to 2025). A malignant neoplasm originating from the surface ovarian epithelium. "CHL1 expression is dysregulated in major epithelial malignancies such as ovarian cancer and esophageal squamous cell carcinoma." (PMID 41374320, 2025). "The issue is a critical one given that mutations in the Chl1 human homologs ChlR1/DDX11 and BACH1/BRIP1/FANCJ collectively result in Warsaw Breakage Syndrome, Fanconi anemia, cell aneuploidy and breast and ovarian cancers." (PMID 29186203, 2017). "Mutations in CHL1 human homologs BACH1/BRIP/FANCJ and ChlR1/DDX11 helicases collectively result in Warsaw Breakage Syndrome, Fanconi anemia, breast and ovarian cancers." (PMID 29186203, 2017). "Chl1 is of further import because it is the homolog of both ChlR1/DDX11 and BACH1/BRIP/FANCJ, mutations in which result in Warsaw Breakage Syndrome and both Fanconi anemia and breast and ovarian cancers, respectively." (PMID 24086532, 2013). "CHL1 and ITGA8 were identified as specific potential biomarkers for renal and ovarian cancer, respectively." (PMID 25997610, 2015).
esophageal squamous cell carcinoma (5 papers, 2017 to 2025). Esophageal squamous cell carcinoma (ESCC) is a type of esophageal carcinoma (EC) that can affect any part of the esophagus, but is usually located in the upper or middle third. "Meanwhile, because of the loss of 3p26.3, CHL1 gene was also reported as a candidate tumor suppressor gene in oral squamous cell carcinoma and esophageal squamous cell carcinoma." (PMID 29568376, 2018). "However, single-nucleotide polymorphism (SNP)-mass array demonstrated the absence and down-regulation of CHL1 expression in primary esophageal squamous cell carcinoma (ESCC) tumors and ESCC cell lines." (PMID 29089868, 2017). "CHL1 is an inhibitory oncogene in many tumors, which is involved in the inhibition of cancer cell proliferation, epithelial–mesenchymal transition (EMT), and even chemotherapy resistance, like esophageal squamous cell carcinoma and renal carcinoma." (PMID 36727070, 2022).
nasopharyngeal carcinoma (5 papers, 2018 to 2024). A carcinoma arising from the nasopharyngeal epithelium. "In conclusion, this study reveals CHL1 as a tumor suppressor gene for both nasopharyngeal carcinoma progression and metastasis." (PMID 31523184, 2019). "Both in vitro (cell growth rate and foci formation) and in vivo (tumor formation in nude mouse) assays showed that CHL1 has a potent inhibitory effect on nasopharyngeal carcinoma cells." (PMID 31523184, 2019). "In view of the important role of Akt and Merlin in the development of tumor, a more comprehensive understanding of the mechanism of CHL1 in nasopharyngeal carcinoma will provide a more effective therapeutic strategy for the treatment of nasopharyngeal cancer patients." (PMID 31523184, 2019). "A putative TSG called cell close homologue of L1 (CHL1, also known as CALL) located at 3p26 loci was identified because it is commonly deleted in lung, esophageal and nasopharyngeal carcinoma respectively." (PMID 31523184, 2019). "Furthermore, ectopic expression of CHL1 in nasopharyngeal carcinoma cells inhibited their clonogenicity and migration as compared with parental cells without CHL1 expression." (PMID 29899830, 2018).
colon adenocarcinoma (4 papers, 2018 to 2022). "For example, Yu et.al demonstrated that miR-21-5p facilitated the proliferation and invasion of colon adenocarcinoma through CHL1." (PMID 36522730, 2022). "A recent study demonstrated that inhibiting the CHL1 expression by microRNA-21 increases the invasiveness of tumor cells in colon adenocarcinomas." (PMID 32284790, 2020). "MiR-21-5p expedites the growth and invasion of colon adenocarcinoma cells by targeting CHL1." (PMID 34905503, 2021). "In addition, a down-regulation of CHL1 via overexpression of miR-21-5p promotes the propagation and invasion of tumor cells in colon adenocarcinomas." (PMID 32284790, 2020). "This study aims to investigate the effect of miR-21-5p on process of colon adenocarcinoma (COAD) cells and its connection with neural cell adhesion molecule L1 (CHL1)." (PMID 30134821, 2018).
colorectal cancer (4 papers, 2015 to 2020). A primary or metastatic malignant neoplasm that affects the colon or rectum. "The methylation of five genes (AHCYL2, IL11RA, SEMA6D, BIRC3, and HADHB) was associated with tumors, and four genes (IL11RA, CHL1, SEMA6D, and BIRC3) were associated with colorectal cancer." (PMID 29507648, 2018). "Interestingly, the CHL1 gene is hypermethylated in DNA samples from African American patients with colorectal carcinoma." (PMID 33240104, 2020).
CRASH syndrome (4 papers, 2013 to 2022). "Similar axon targeting phenotypes have also been reported upon knock-out of L1 family members Nrcam and Chl1 while L1 knockout mice succumb to the much more severe CRASH syndrome with corpus callosum hypoplasia and mental retardation." (PMID 26802628, 2016). "Finally, our structural and biochemical analysis indicated that L1 syndrome-associated mutations in L1CAM, a member of the L1 immunoglobulin family proteins including Nfasc, L1CAM, NrCAM, and CHL1, compromise binding with ankyrins." (PMID 35850303, 2022).
developmental delay (4 papers, 2013 to 2023). "Heterozygous loss of the CHL1 gene has been observed in individuals with cognitive delays, though a definitive statistical association has not yet been conducted." (PMID 37254169, 2023). "If the association with CHL1 and cognitive delay is confirmed, this finding may have therapeutic potential in that CHL1 expression levels could be manipulated through targeting epigenetic engineering tools in progenitors to this enhancer region." (PMID 37254169, 2023).
epilepsy (4 papers, 2014 to 2018). A brain disorder characterized by episodes of abnormally increased neuronal discharge resulting in transient episodes of sensory or motor neurological dysfunction, or psychic dysfunction. "Epilepsy was also present in one child with a submicroscopic 3p26.3 noncontiguous terminal deletion containing only the CHL1 gene." (PMID 24778888, 2014). "Interestingly, the previously reported 3p26.3 microduplication case manifested similar clinical features to those patients carrying a CHL1 gene deletion, namely, nonspecific intellectual disability and epilepsy." (PMID 24778888, 2014).
mental disorder (4 papers, 2018 to 2023). A disease that has its basis in the disruption of mental process. "Mice constitutively lacking CHL1 (CHL1−/−) show behavioral deficits congruent with psychiatric disorders." (PMID 29497366, 2018).
papillary thyroid carcinoma (4 papers, 2016 to 2019). "Similarly, miR-182 suppresses the expression of CHL1 mRNA through direct targeting of the 3′-untranslated region (3′-UTR) in papillary thyroid carcinoma." (PMID 29899830, 2018). "Interestingly, microRNA-182 is a negative regulator of CHL1 in human papillary thyroid carcinoma (PTC) with overexpression of miR-182 suppressing CHL1 and therefore promoting PTC cell proliferation and invasion." (PMID 27111221, 2016).